AKT1 (AKT serine/threonine kinase 1)
Diseases named in the same sentence as AKT1 in open-access papers (continued):
Sharing a sentence is not in itself a finding about the gene and the disease.
cancer (continued). "In spite of their similarity in primary structure and substrate specificity, Akt1 and Akt2 isoforms play opposite roles in cell migration and cancer cell metastasis." (PMID 25575302, 2015). "The majority of Akt1 was cytosolic in differentiated cancers whereas two of three anaplastic cancers showed lower cytosolic and higher nuclear Akt1 expression." (PMID 26793165, 2015). "The other component of the hub, AKT1 plays an important role in proliferation, survival, migration and metastatization of many cancers including OS." (PMID 26123714, 2015). "In cellular assays, both ARQ 092 and/or ARQ 751 potently inhibited elevated AKT activity and showed pathway knockdown in cancer cell lines driven by PIK3CAH1047R, PTEN null, and AKT1-E17K mutations." (PMID 26469692, 2015). "Mutations in AKT1 at the PHD–KD interface, as is the case here, that weaken their interaction have been previously reported in human cancers." (PMID 26137586, 2015). "Since apoptosis is reported to take place in wasting muscle in cachexia, several other studies evaluated the key role of Akt1 in developing cancer cachexia." (PMID 25238546, 2014). "Specifically, upregulation and activation of AKT1 is required to sustain a hypermetabolic state (e.g., “Warburg effect”) that is a unique characteristic of certain cancer cells." (PMID 24628780, 2014). "Akt1 promotes cell proliferation and survival and counteracts apoptosis induced by anti-cancer drugs." (PMID 24848107, 2014). "They find several cancer biology relevant genes, such as AKT1, ARNT, and PMS2 and their literature analysis finds that 57% of the BEDMRs overlap with at least one gene that has more than three literature references related to cancer." (PMID 24653980, 2014). "Active STAT5 and AKT1 both mediate evasion from apoptosis and self-sufficiency in growth signals, which are hallmarks of cancer." (PMID 24628780, 2014). "Previously we found that the BRCA1-AKT1 pathway contributes to tumorigenesis and that the AKT1/mTOR is a novel therapeutic target for BRCA1-deficient cancers." (PMID 24831086, 2014). "DAVID ontology analysis revealed enrichment of cancer-associated pathways, including the well-characterized cancer genes MTOR, EGFR, AKT1, and CASP8 in the region of overlap." (PMID 25294808, 2014). "The log fold change of genes involved in important pathways in cancer in DLD-1 AKT2 KO versus AKT1 KO." (PMID 24760019, 2014). "In particular, Akt1 and Akt2 seem to have opposing roles in cancer metastasis despite the similarity of their activation mode by PI3K stimulation." (PMID 25309720, 2014). "Similar to the regulation of AKT1 during normal mammary gland development, cancer cells are able to upregulate this serine-threonine kinase on the transcriptional level to meet the specific metabolic needs in the transformed state." (PMID 24628780, 2014). "When PIK3CA and AKT1 are downstream effectors of RAS, both HRAS and RAC1 are RAS superfamily of small GTPases that cause cancer growth, invasion, and metastasis." (PMID 25356910, 2014). "In mice as well as humans, the Akt1 gene is transcriptionally upregulated in a subset of cancer cells, and the growth factor-dependent activation activation of this locus occurs through at least two distinct promoters." (PMID 24628780, 2014). "AKT1 (v-akt murine thymoma viral oncogene homologue 1) kinase is a member of possibly the most frequently activated proliferation and survival pathway in cancer." (PMID 23741320, 2013). "Mutations and/or amplifications of the PI3K catalytic subunits p110α (PIK3CA) and p110β (PIK3CB), the PI3K regulatory subunits p85α (PIK3R1) and p85β (PIK3R2), the PI3K effector AKT (AKT1) are often observed in cancer." (PMID 23658859, 2013).
cancer (continued). "In the present study, we presented evidences on the crosstalk between PI3K-Akt and NFκB pathways after ectopic and endogenous BTG2 expressions in normal and cancer cells via activation of Akt1 and degradation of IκBα protein." (PMID 24047462, 2013). "AKT1 (v-akt murine thymoma viral oncogene homologue 1) kinase is one of the most frequently activated proliferated and survival pathway of cancer." (PMID 23741320, 2013). "We genotyped 8 potentially functional polymorphisms in AKT1, AKT2, PTEN and MTOR genes using the TaqMan method in a case-control study of 710 RCC patients and 760 cancer-free subjects." (PMID 23209702, 2012). "It has been reported recently that oncogenic Akt1 can repress HRR by inducing cytoplasmic retention of Brca1 in human cancer cells." (PMID 22481935, 2012). "More PIK3CA/AKT1 mutations and PIK3CA copy gain are identified in ATC as compared to well differentiated cancer, suggesting that PI3K/mTOR pathway activity is involved in the process of cancer de-differentiation." (PMID 23077520, 2012). "BEDMR loci are further associated with local hypomethylation (66%), concentrations of the Alu SINE repeats within 3 Mb (35% of the cases), and tend to occur near a number of cancer related genes such as the protocadherins, AKT1, DUB3, GAB2." (PMID 23293768, 2012). "In many cancers, PI3K/AKT pathway activation is mediated by oncogenic mutations in PIK3CA and AKT1 genes." (PMID 22363598, 2012). "RX-0201 downregulated Akt-1 expression at nanomolar concentrations in multiple types of human cancer." (PMID 23085539, 2012). "Since it thereby promotes cell survival, Akt1 has been regarded as a major factor in many types of cancer." (PMID 22107784, 2011). "Ingenuity pathway analysis indicated several altered biological functions as a result of Akt1 ablation, including cell-to-cell signaling, intercellular interaction, tissue morphology, organismal development, and cancer within the top ten altered functions." (PMID 21915327, 2011). "Using these tools, we have recently found that Akt1–3 are localized mainly to the cytoplasm, the mitochondria, and the nucleus, respectively, in many cancer cell lines including cervical, breast, and prostate cancer cells." (PMID 21297943, 2011). "Akt1 seems to play critical role in cell survival and is overexpressed in high grade and stage carcinomas of prostate, breast and ovary." (PMID 21407808, 2011). "The critical role of Akt1 in cell survival was also found in high grade and stage carcinomas of prostate, breast and ovary." (PMID 21407808, 2011). "Previously, we reported on the E17K substitution in AKT1 in a ductal adenocarcinoma of the prostate in a patient who had a very long cancer-specific survival." (PMID 20407443, 2010). "AKT1 is a serine/threonine kinase that functions as a central element in the cell survival pathway and is activated in many cancers." (PMID 20520724, 2010). "On the other hand, the PI3K inhibitor Ly294002 or a dominant-negative Akt1 sensitized cancer cells to chemotherapy." (PMID 16168126, 2005). "To investigate the role of Akt in the modulation of the onset of anoikis and of chemosensitivity in cancer cells we designed a novel form of constitutively active Akt1." (PMID 12373610, 2002). "STAT3 and AKT1 consistently emerged as common top-scoring hub genes in both cancers." (PMID 41829818, 2026). "Therefore, this study aimed to identify novel natural compounds that can specifically interfere with this crucial oncogenic signaling node by targeting Akt1, aligning with current strategies for developing more precise cancer therapeutics." (PMID 40798865, 2025). "Furthermore, we show that targeting SVIL‐AS1 can sensitize AKT1E17K cancer cells to AKT1 allosteric inhibitor and the PI3Kα inhibitor." (PMID 40135844, 2025).
cancer (continued). "We found that SVIL‐AS1 could enhance the proliferation of cancer cells with AKT1E17K mutation by interacting with PPP2R2A and preventing AKT1 dephosphorylation." (PMID 40135844, 2025). "Furthermore, the molecular docking analysis results were consistent with the findings from the in vitro study, thereby supporting the potential of compound 36 as an AKT1 inhibitor for cancer therapy." (PMID 40141117, 2025). "In this review, we outline therapeutic targets in PI3K/AKT/MTOR signaling in solid tumors, the current state of using inhibitors of this pathway to treat patients whose cancers possess activating mutations in PIK3CA, AKT1/2, or MTOR, and exciting new inhibitors that are entering clinical trials." (PMID 40564038, 2025). "Akt1 is a critical node in cancer progression, influencing diverse signaling pathways." (PMID 40798865, 2025). "Therefore, targeting Akt1 or its regulators holds promise as a novel therapeutic strategy against various cancers." (PMID 40798865, 2025). "Hyperactivation of the pathway due to PTEN deficiency or activating mutations in the catalytic subunit alpha of phosphatidylinositol-3-kinase (PIK3CA) and in AKT1 is implicated in tumor growth across cancer indications; hence, the PI3K/AKT pathway has been a target of oncology drug discovery." (PMID 40153000, 2025). "It was hypothesized that ART directly bound to AKT1, thereby inhibiting its activity and exerting an anti-cancer effect in BLCA." (PMID 40303931, 2025). "The current network pharmacology-based analysis of A. laxiflora suggested that compounds (quercetin, 3-acetylursolic acid, and 3-acetyloleanolic acid) in this plant can influence key cancer-associated targets EGFR, AKT1, SRC, and MAPK1 through the PI3K-Akt, MAPK, Ras, and Rap1 signaling pathways." (PMID 40283942, 2025). "The activation of AKT1 can inhibit apoptosis, positively regulate cell proliferation, as well as promote cell migration, and it can exert a regulatory influence in a range of cancers." (PMID 40564394, 2025). "In addition, studies have shown that ginsenoside CK can inhibit the activity of AKT1 in cancer cells, thereby increasing the expression levels of the apoptotic proteases Caspase-3, Caspase-8, and Caspase-9, and inducing apoptosis in cancer cells." (PMID 40422575, 2025). "Notably, Kaempferol 3‐rutinoside‐4′‐glucoside and Kaempferol 3‐rutinoside‐7‐sophoroside exhibited substantially higher binding affinities compared to Ipatasertib, presenting innovative therapeutic candidates for the treatment of Akt1‐driven cancers." (PMID 40798865, 2025). "Hence, it is possible that the anti-cancer properties of PC were aided by a decrease in the active form AKT1 and ERK1/2 and the downregulation of Cyclin D1, Cyclin E, and EMT pathway genes." (PMID 40319292, 2025). "Nevertheless, PI3K/AKT pathway activation in cancer can also be enhanced by mechanisms other than alterations in PIK3CA/AKT1/PTEN14,25,26, supported by preclinical data showing that capivasertib inhibited growth in some cell lines without PIK3CA/AKT1/PTEN alterations." (PMID 40346047, 2025). "•Network analysis linking DEPs, phosphoproteins, and TFs, highlight AKT1 as key cancer driver." (PMID 41237900, 2025). "The targets EGFR and AKT1 are proteins that promote cancer occurrence." (PMID 39598341, 2024).
cancer (continued). "Comparing doxycycline treated (DOX + ) to untreated cells (DOX-), we observed significant increases in several signaling pathways known to impact cancer cell proliferation and survival, including increased phosphorylation of AKT1/2/3 at T308, STAT3 S727, and p70 S6 kinase, to name a few." (PMID 38182652, 2024). "This could suggest that suppression of IKK1/α could possibly halt other pathways due to its wide array of interaction with other proteins, such as IKK2/β, AKT1, MAP4K4, and TRAF2, that are possibly implicated with other cancer pathways." (PMID 39062574, 2024). "Gene expression analysis suggests that its mechanism of action may involve downregulation of cancer-related genes such as AKT1, BCL2L1, CCND1, CDK4, PLK1, and RHOA." (PMID 38751791, 2024). "AKT1 had a frameshift deletion of 11 base pairs in an initial clone and the oncogenic variant AKT1E17K in a disseminated clone of 2 triple-proficient cancers." (PMID 38175731, 2024). "Therefore, phenotypic changes observed in Akt1/2/3KO cancer cells were unlikely due to the down-regulation of MAPK signaling." (PMID 38920688, 2024). "Moreover, it successfully differentiated between CTCs from patients with different Akt1 genotypes, highlighting its potential to determine the activation status of druggable cancer driving proteins for individual and targeted treatment decision making." (PMID 39304879, 2024). "Additionally, LINC01405 upregulation led to the increased cell populations, proliferation, and upregulation of critical cancer‐related genes, including AKT1, AKT3, mTOR, WNT3A, SMAD3, CYCLIN D1, CYCLIN D2, BCL2, and GSK3B." (PMID 38225865, 2024). "Numerous miRNAs can target the AKT1 protein to regulate this protein in cancer cells." (PMID 38836981, 2024). "However, SGK1 phosphorylation markedly increases under genotoxic stress, indicating a potential role in promoting survival and resistance to some chemotherapeutics, particularly AKT1 inhibitors in cancer cells." (PMID 37343701, 2023). "P21, Caspase-9, and AKT-1 were down, as well as a drop in cancer cells." (PMID 37570875, 2023). "These target genes are involved in and drive many biological pathways that determine this more aggressive phenotype, for example the overexpression of AKT1 drives cell cycle progression and cell survival of these cancer cells thus increasing cell proliferation." (PMID 36937454, 2023). "AKT1, being involved in various cancers, obviously affects apoptosis." (PMID 37766164, 2023). "AKT1 protein plays an important role in the development of cancer therapies." (PMID 36982429, 2023). "Thus, AKT1 inhibition is a treatment option undergoing clinical trials for several cancers, including PCa." (PMID 36937454, 2023). "Through the PI3K-Akt, HIF-1, and ErbB signaling pathways, curcuma regulates key targets that are involved in angiogenesis, cancer cell proliferation, metastasis, invasion, and chemotherapy resistance, including AKT1, TNF, STAT3, EGFR and HSP90AA1, in the treatment of OS." (PMID 37311820, 2023). "Furthermore, in silico study revealed that plumbagin can bind to cancer signaling proteins, namely PI3Kγ, AKT1/PKBα, Bcl-2, NF-κB, and Stat3, which play a key role in the pathogenesis of cancer." (PMID 37110873, 2023). "Overall the genomic landscape was stable, with pathogenic or likely pathogenic alterations being identified in 51 cancer genes, with 9 (18%) of them showing alterations being recurrent across different samples (MYCN, CDKN2A/2B, CDK4, GLI1, AKT1, IGF2, MED12, NCOR2)." (PMID 37730754, 2023).
cancer (continued). "Finally, the molecular docking and core ingredients analysis showed that quercetin was the core ingredient of JQH and bound well with several inflammation-cancer targets, including AKT1, EGFR, HIF1A, and IL6A." (PMID 37964307, 2023). "Therefore, we evaluated the inhibitory properties of four phytochemicals, isoliquiritigenin, shogaol, tehranolide, and theophylline, against AKT1, a cancer therapeutic molecular target, using molecular docking." (PMID 36985568, 2023). "Natural compounds targeting AKT1 can be employed to control pathways with anti-cancer effects." (PMID 36985568, 2023). "Constitutive activation of the PI3K/AKT signaling pathway by AKT1 occurs in various cancers." (PMID 36994237, 2023). "If there was a clinical trial indication at level C or D for a specific cancer type, such as amplification of MDM2 or FGFR1 or mutations of AKT1, ATM, CDK12, and PTEN, patients were considered as candidates for receiving treatment, although in most cases, no clinical trials were available." (PMID 36251535, 2023). "As a consequence, the full potential of capivasertib in AKT1-mutant cancers may require drug combination." (PMID 36765661, 2023). "Here, we hypothesize that aPKCs are essential for NB progression while 14-3-3 and Smad2/3 play central roles by coordinating aPKCs in the cell cycle (via the aPKC/Cdk7/Cdk2 pathway) and cancer progression via Akt1/NFκB/TGF-β pathways." (PMID 36776326, 2023). "In addition, several AKT1 inhibitors are being developed to control OSCC and other associated forms of cancers." (PMID 35887580, 2022). "In addition, it was observed that the expression of miR-145 was increased in these cells with low expression of pAkt1, indicating that miR-145 expression is inversely correlated with activated Akt1 in these cancer cell lines." (PMID 35563814, 2022). "GNE-493 was still cytotoxic and induced apoptosis in Akt1/2-silenced cancer cells." (PMID 35296639, 2022). "miR-145, which is frequently downregulated in cancer cells with activated Akt1, may play an important role in Akt1-induced radioresistance, at least in part by modulating DNA-PKcs expression." (PMID 35563814, 2022). "AKT1 acts as a positive regulator of different types of cancers, especially OSCC." (PMID 35887580, 2022). "N stage cancer patients are significantly less inclined to harbor BRAF, ROS1 and AKT1 mutations." (PMID 36429016, 2022). "Interestingly, the right‐sided tumors have significantly higher phospho‐ERK2 and phospho‐Akt1/2/3 than left‐sided tumors, re‐affirming the different cancer biology between right‐ and left‐sided colon." (PMID 34919787, 2022). "Additionally, the correlation analysis from the same TCGA pan-cancer data showed that PARP1 expression strongly correlated with AKT1 expression." (PMID 36203459, 2022). "AKT1 mediates various aspects of cancer development and progression, including in CC cells." (PMID 36566195, 2022). "Indeed, the analysis of hotspot regions in genes such as ERBB4, AKT1, FGFR2 and MLH1 underline that specific alterations in the primary tumor are extremely important for cancer prognosis prediction." (PMID 36077746, 2022). "In addition, PI3K/AKT/mTOR is one of the most mutated signaling pathways in human cancers, usually correlated with the loss of PTEN and mutations in PIK3CA (encoding PI3K-p110α) and AKT1." (PMID 36077529, 2022). "The silence of AKT1 not only abolished the properties of metastasis but also inhibited the expression of epithelial to mesenchymal transition markers, such as vimentin protein which is related to invasive cancers." (PMID 35646655, 2022).